HIF1A (hypoxia inducible factor 1 subunit alpha)
Diseases named in the same sentence as HIF1A in open-access papers (continued):
Sharing a sentence is not in itself a finding about the gene and the disease.
osteosarcoma (continued). "In neuroblastoma cells, HIF1A regulates the sonic hedgehog signaling pathway to promote the invasive abilities of cancer cells; in human osteosarcoma tissue, expression of differentiated embryonic chondrocyte gene 2 (DEC2) and HIF1A is closely related to poor prognosis." (PMID 35659268, 2022). "In 3D cultures of ABCB1-high/ABCA1-low chemo-immune-resistant cells, expression of the doxorubicin effluxer ABCB1 was upregulated by the Ras/ERK1/2/HIF-1α signaling axis, which suggests the existence of pathway crosstalk to reinforce an already chemoresistant phenotype in osteosarcoma cells." (PMID 36232719, 2022). "Three meta-analyses recently concluded that HIF-1α expression might be an effective predictive factor of poor prognosis in osteosarcoma." (PMID 35158767, 2022). "Intriguingly, blockade of HIF1α efficiently weakened the tumorigenesis of Saos-2 and MG-63 cells in vivo, demonstrating that TGF-β could further promote osteosarcoma stemness through HIF1α." (PMID 34763667, 2021). "Given the crucial role of HIF1α in tumorigenesis and chemoresistance, it might be feasible to target HIF1α to improve the outcome of chemotherapy in osteosarcoma." (PMID 34763667, 2021). "We speculated that NUSAP1 was the downstream target of HIF-1α transcriptional regulation and participates in the regulation of osteosarcoma cell migration and invasion in a HIF-1α-dependent manner." (PMID 34322597, 2021). "According to the evidence, CCL4 promotes integrin αvβ3 expression through the CCR5 receptor and then activates the FAK/AKT/HIF-1α signaling pathway, which subsequently inhibits miR-3927-3p expression and promotes integrin αvβ3 expression, as well as osteosarcoma cell migration." (PMID 34884541, 2021). "In addition, studies have shown that ANGPTL2 is highly expressed in osteosarcoma cells induced by hypoxia / HIF-1α and promotes cell proliferation, invasion, migration and G1 phase arrest." (PMID 33203792, 2020). "HIF-1α has been reported to have a direct linkage with the ABCB1-mediated chemoresistance in osteosarcoma: indeed, HIF-1α is induced during the acquisition of doxorubicin resistance by the continuous exposure to the drug and in turn, it mediates the resistance to doxorubicin by up-regulating ABCB1." (PMID 32155954, 2020). "Moreover, it was found to negatively regulate HIF-1α expression through transcriptional activation of osteosarcoma amplified 9 (OS-9)." (PMID 32640630, 2020). "Apart from that, by competitively binding miR-143-5p, TUG1 could enhance the expression of HIF-1α (hypoxia inducible factor 1 subunit alpha), thereby facilitating the metastasis of osteosarcoma cells." (PMID 33520725, 2020). "We speculated that HMGN5 may be a downstream factor of HIF1A which plays an important role in osteosarcoma metastasis under hypoxic conditions." (PMID 31930127, 2019). "Like AUF1 and VEGF-A, HIF-1α was also highly expressed in the most aggressive osteosarcoma cells." (PMID 31448053, 2019). "This phenomenon is important for secondary tumor events as hypoxia can independently induce the epithelial–mesenchymal transition (EMT), a crucial step in cancer progression and metastasis via a number of mechanisms such as HIF-1α expression in osteosarcoma and osteosarcoma cells." (PMID 31765423, 2019). "Overexpression of HIF1A has been reported to indicate poor prognosis in osteosarcoma patients." (PMID 31930127, 2019). "We examined HIF-1α mRNA expressions in 45 osteosarcoma specimens with immunohistochemical staining." (PMID 28442599, 2019). "In summary, our xenograft mouse model revealed that miR-199a could sensitize cisplatin resistant osteosarcoma cells through inhibition of HIF-1α in vivo." (PMID 28442599, 2019). "Finally, by analysing the clinical osteosarcoma patient samples, we demonstrate a reverse correlation between miR-199a and HIF-1α mRNAs." (PMID 28442599, 2019). "We next investigated whether there is direct regulation between miR-199a and HIF-1α in osteosarcoma cells." (PMID 28442599, 2019).
osteosarcoma (continued). "It is suggested that HMGN5 may be an important downstream factor for HIF1A to promote osteosarcoma metastasis." (PMID 31930127, 2019). "However, it has been reported that downregulation of the hypoxia regulator HIF1α promotes IDH in osteosarcoma, which provides an explanation for the greater conversion from 5mC to 5hmC mediated by TET enzymes." (PMID 30558637, 2018). "Immunohistochemical labelling for the hypoxia marker HIF-1α in clinically derived osteosarcoma tumour samples correlates with pathologic stage, and tumours from patients with medium to strong HIF-1α expression had decreases in both overall survival and disease-free survival." (PMID 29098360, 2018). "HIF-1α also functtions in anaemia induced- doxorubicin resistance of human osteosarcoma cells." (PMID 29661211, 2018). "In this study we explored the influence of HIF-1α gene silencing on angiogenesis in osteosarcoma." (PMID 28523034, 2017). "Overexpression of HIF-1α protein was detected in 79% of osteosarcoma tumors." (PMID 26393682, 2015). "While the detailed mechanism underlying the DEC2-facilitated stabilization of HIF-1α in osteosarcomas remains to be further explored, our results indicate that DEC2 could promote osteosarcoma invasiveness and metastasis by enhancing HIF-1 function." (PMID 25884381, 2015). "However, in our study, hypoxia upregulated the transcription of the CXCR4 gene by enhancing the transcription factor HIF-1α and thus promoted cell migration in human osteosarcoma." (PMID 24618817, 2014). "We performed immunohistochemistry, immunocytochemistry, quantitative real-time PCR, Western blots and fluorescent reporter assays to evaluate the correlation between CXCR4 and HIF-1α expression in human osteosarcoma specimens or SOSP-9607 cells under normoxic and hypoxic conditions." (PMID 24618817, 2014). "The novel finding of HIF-1α independent drug resistance suggests however other hypoxia related targets may be more relevant in paediatric osteosarcoma." (PMID 23785417, 2013). "In conclusion, we provide strong evidence that CoCl2 has the ability to inhibit osteosarcoma development; the mechanism may be related to the hypoxic microenvironment and HIF-1α may be a critical regulatory factor." (PMID 23426939, 2013). "Therefore, we recommend that regulating RUNX2 and HIF-1α and addressing their molecular interactions is a crucial therapeutic target for osteosarcoma, which could enhance overall and disease-free survival." (PMID 40806771, 2025). "Thus, radiotherapy resistance in osteosarcoma may be caused by the combined action of RUNX2 and HIF-1α." (PMID 40806771, 2025). "This new approach of considering RUNX2/HIF-1α as an integral transcription factor in osteosarcoma may aid in mitigating tumour development, improving treatment resistance, and accelerating the overall survival rate of patients with osteosarcoma." (PMID 40806771, 2025). "Therefore, regulation of these two major factors, RUNX2 and HIF-1α, may help overcome chemotherapeutic resistance, enhance overall and disease-free survival in patients with osteosarcoma, and stand out as an effective therapeutic approach." (PMID 40806771, 2025). "Similarly, HIF-1α promotes metabolic alterations that aid in the progression of osteosarcoma, and its elevated expression is more likely to result in poor clinicopathological traits, advanced cancer stage, metastasis, low survival, and resistance to chemotherapy." (PMID 40806771, 2025). "Hence, our review focused on highlighting the intricate network between RUNX2 and HIF-1α, which support each other or may work synergistically to develop resistance to therapy and osteosarcoma progression." (PMID 40806771, 2025). "Thus, there may be an intricate relationship between RUNX2 and HIF-1α that allows them to complete each other or may work synergistically to develop resistance to therapy and promote osteosarcoma progression." (PMID 40806771, 2025).
osteosarcoma (continued). "Furthermore, siRNA mediated specific inhibition of HIF-1α inhibited angiogenesis in osteosarcoma." (PMID 31448053, 2019). "However, a recent study found that HIF-1α might play an important role in the evolution of osteosarcoma." (PMID 30782196, 2019). "Then inhibiting angiogenesis via blocking HIF-1α expression may one of the targeting crucial steps in treating hypoxic tumor cells, is expected to provide a novel and attractive target of therapeutic strategies of osteosarcoma." (PMID 28523034, 2017). "In certain contexts (e.g., osteosarcoma PDT), TRPV1 activation reduces oxygen consumption and HIF-1α accumulation, biasing toward ferroptosis—emphasizing that TRPV1 outputs depend on dose, duration, and metabolic state." (PMID 41303593, 2025). "Together, RUNX2 and HIF-1α collaboratively enhance the metastatic and invasive potential of osteosarcoma, where RUNX2 upregulates MMPs and other enzymes to degrade the extracellular matrix and HIF-1α supports this process through EMT." (PMID 40806771, 2025). "Studies have shown that the increased expression of miRNA-216b can regulate the JMJD2C/HIF1α/HES1 signaling axis in osteosarcoma cells, thereby increasing cisplatin-induced apoptosis and effectively treating osteosarcoma." (PMID 39857292, 2025). "This evidence indicates that knockdown of HIF-1α reduces the promoting effects induced by MATN4 overexpression on the proliferation, migration and invasion of osteosarcoma cells under hypoxia." (PMID 38889378, 2024). "Similar results were also obtained in osteosarcoma MG-63 cells, where results pointed toward a role of melatonin in suppressing the EMT via HIF-1α/Snail/MMP-9 signaling." (PMID 38473317, 2024). "In this scenario, the mechanisms that bring to the loss of HIF1-α ubiquitination, and to its consequent accumulation, are yet to be fully investigated, but promoting the process may lead to the HIF transcription factor downregulation and possibly to new therapeutic approaches for osteosarcoma." (PMID 38534381, 2024). "ChIP-seq experiments of both factors in the same osteosarcoma cell line showed that BMAL1 and HIF1α share a large portion of binding sites on chromatin, which constitutes approximately a third of all HIF1α targets and a quarter of BMAL1 targets." (PMID 37601651, 2023). "Because we previously reported that the SphK1/S1P pathway is a regulator of both HIF-1α and HIF-2α during hypoxia in multiple cancer cell lineages, we evaluated its relevance with regard to HIF-1α expression in osteosarcoma cells." (PMID 35158767, 2022). "Under hypoxic conditions, Bavachinin decreases the activity of HIF-1α in a concentration-dependent manner in human KB carcinoma and HOS osteosarcoma cells, mainly by raising the interaction between VHL and HIF-1α followed by proteasomal degradation." (PMID 36014432, 2022). "The involvement of SENP1/HIF-1α axis in the regulation of cell viability, EMT and invasion under hypoxia shed a light on its role as potential therapeutic target for osteosarcoma treatment." (PMID 35465332, 2022). "In contrast, FTY720 remarkably reduced cell proliferation to the same extent in normoxic and hypoxic conditions in all osteosarcoma cell lines, suggesting that efficacy of FTY720 was related to its anti-HIF-1α effect." (PMID 35158767, 2022). "We also found a significant increase in HIF1α (hypoxia-inducible factor 1-alpha) expression with a decrease in the inhibitor of HIF1α, OS9 (Osteosarcoma Amplified 9, Endoplasmic Reticulum Lectin)." (PMID 33917306, 2021). "Another study has shown that HAND2-AS1 regulates osteosarcoma metabolism via sequestering fructose-1,6-bisphosphatase 1 (FBP1) from binding to HIF1α thereby increasing the HIF1α expression." (PMID 33652661, 2021). "Both HIF-1α and HIF-2α proteins are expressed in osteosarcoma and giant cell tumour of bone (GCTB), as well as HIF-regulated Glut-127–29." (PMID 33273561, 2020).
osteosarcoma (continued). "In osteosarcoma, proangiogenic lncRNA TUG1 functions via silencing miR-143-5p, increasing the miRNA target HIF-1α." (PMID 32992718, 2020). "M‐CSF induces expression of HIF‐1α protein in human monocytes and osteoclasts and can induce detectable levels of HIF-1α and HIF-2α in MG-63 osteosarcoma cells." (PMID 33273561, 2020). "Here, we show that the rescue of HIF-1α in miR-199a overexpressing osteosarcoma cells enhanced resistance to cisplatin, suggesting an miR-199a-HIF-1α-cisplatin sensitivity axis in osteosarcoma." (PMID 28442599, 2019). "Here, we present clear evidence that AUF1 is highly expressed in the aggressive osteosarcoma cell lines, and positively regulates the expression and secretion of the pro-angiogenic factor VEGF-A and its regulator HIF-1α." (PMID 31448053, 2019). "In summary, the present findings present clear evidence that AUF1 is a master regulator of osteosarcoma angiogenesis through positive regulation of 2 key angiogenic factors VEGF-A and its transcriptional regulator HIF-1α." (PMID 31448053, 2019). "In the next step, we plan to explore the effects of HIF1A and HMGN5 on osteosarcoma cell metastasis by injecting three groups of cells (Cherry-GFP, HIF1AOE-GFP, and HIF1AOE-HMGN5sh) into the tail vein of nude mice." (PMID 31930127, 2019). "We have previously shown that hypoxia-induced gene transcription is regulated by both HIF-1α and HIF-2α in osteosarcoma cells." (PMID 29739381, 2018). "Both isoforms of HIF (HIF-1α, HIF-2α) promote osteosarcoma cell proliferation and migration in vitro." (PMID 29739381, 2018). "Reports in other cell lines described ANGPTL4 as regulated solely by HIF-1α, however hypoxic induction of ANGPTL4 was also regulated by both HIF-1α and HIF-2α in osteosarcoma cells." (PMID 29739381, 2018). "The effect of thapsigargin on HIF1α stabilisation was tested in MCF7 (breast), COV-434 (ovarian) and U2OS (osteosarcoma) treated with thapsigargin and exposed to hypoxia." (PMID 29529249, 2018). "In another study, lncRNA ENST00000563280 and NR-036444 were found to interact with critical cancer genes such as ABCB1, HIF1A, and FOXC2 to modulate doxorubicin-resistance in osteosarcoma patients." (PMID 28122578, 2017). "In conclusion, WISP-1 enhances VEGF-A expression in osteosarcoma and promotes EPC angiogenesis through integrin αvβ3 and the FAK/JNK/HIF-1α pathways, as well as via down-regulation of miR-381 expression." (PMID 28406476, 2017). "Since DEC2 has been reported as a regulator of HIF-1α stability in breast and endometrial cancers, we next asked if DEC2 negatively correlates with HIF-1 activation in osteosarcoma." (PMID 25884381, 2015). "DEC2 knockdown in osteosarcoma cell lines (U2OS, MNNG and 143B) attenuated HIF-1α accumulation and impaired the up-regulation of HIF-1 target genes in response to hypoxia." (PMID 25884381, 2015). "Taken together, whereas DEC2 was found to promote HIF-1α degradation in other types of tumors, our data indicate that DEC2 facilitates HIF-1α stabilization and promotes HIF-1 activation in osteosarcoma." (PMID 25884381, 2015). "While DEC2 facilitates HIF-1α stabilization, HIF-1 activation also upregulates DEC2 expression, forming a vicious cycle in osteosarcoma." (PMID 25884381, 2015). "Either hypoxia or DFX treatment was able to stabilize HIF-1α; the normoxic stabilization of HIF-1α by DFX exposure effectively upregulated DEC2 expression, indicating HIF-1 activation is sufficient to enhance DEC2 expression in osteosarcomas." (PMID 25884381, 2015). "To investigate the involvement of HIF-1α and DEC2 in the progression and metastasis of osteosarcoma, we used a cohort of 50 primary osteosarcoma samples obtained from clinical patients." (PMID 25884381, 2015). "Having demonstrated that hypoxia-induced CXCR4 expression was regulated by HIF-1α in osteosarcoma cell lines, we next investigated the correlation between CXCR4 and HIF-1α expression in 98 osteosarcoma cases." (PMID 24618817, 2014).
osteosarcoma (continued). "Hypoxia rapidly stabilised HIF-1α and HIF-2α in all three osteosarcoma cell lines and the corresponding up-regulation of CA IX protein levels, Glut-1 mRNA levels and levels of secreted VEGF-A, indicates that it is transcriptionally active in these cell lines." (PMID 23785417, 2013). "To identify new mediators of the HIF1A-mediated hypoxia pathway, we used U2OS osteosarcoma cellsstably expressing a firefly luciferase reporter construct fused to three tandem copies of the iNOS(inducible nitric oxide synthase) HRE (hypoxia-response element)." (PMID 23398456, 2013). "We treated osteosarcoma cell lines with anti-tumor agent and some specific inhibitors including ERK inhibitor, HIF1-α inhibitor, JAK2 inhibitor, LY294002, and others but we were unable to inhibit EGR1 expression effectively." (PMID 21283769, 2011). "Hypoxia induces expression of HIF-1α and VEGF in the osteosarcoma cell lines Saos2, 143B, U2-OS and MG-63, with MG-63 also expressing HIF-2α." (PMID 20637078, 2010). "Hypoxia induced HIF-1α and HIF-2α in Ewing's and osteosarcoma cell lines while hypoglycaemia specifically induced HIF-2α in Ewing's." (PMID 20637078, 2010). "We have therefore analysed characteristics of the induction of HIF-1α, HIF-2α and HIF target genes in a panel of osteosarcoma and Ewing's sarcoma cell lines and investigated effects of isoform-specific HIF siRNA on the hypoxic phenotype of these cells." (PMID 20637078, 2010). "Therefore, this study emphasizes the significance of HIF-1α and RUNX2 in osteosarcoma and reinforces the need to regulate these two vital factors to establish an effective osteosarcoma treatment." (PMID 40806771, 2025). "Interestingly, knockdown of HIF-1α reduces the stimulatory effects of MATN4 overexpression on the proliferation, migration, and invasion of osteosarcoma cells under hypoxic conditions." (PMID 38889378, 2024). "Additionally, CCL4 facilitates the migration of osteosarcoma cells by activating signaling pathways such as focal adhesion kinase (FAK), protein kinase B (AKT), and hypoxia-inducible factor 1 subunit alpha (HIF-1α)." (PMID 39364412, 2024). "Moreover, HIF-1α can be regulated by USP7, which is upregulated in osteosarcoma and has been found related to the activation of EMT." (PMID 38534381, 2024). "These engage with genes including ABCB1, HIF1A and FOXC2, which may contribute to elevated levels of osteosarcoma resistance to DXR." (PMID 39015175, 2024). "Osteosarcoma cells colonize the lungs more quickly by upregulating ICAM1 expression in response to tumor‐derived IL‐6, which facilitates glycolytic metabolism in tumor cells by activating the MEK/ERK/HIF‐1α pathway." (PMID 36772869, 2023). "In addition, HIF-1α-induced promotion of metastasis and EMT in osteosarcoma cells has been shown to depend on a reduction of intracellular ROS production." (PMID 36701089, 2023). "This uncontrolled HIF1A activation, which promotes HIF1A expression with DEC2, ultimately contributes to the transcriptional reprogramming, metabolic reprogramming, angiogenesis, and invasiveness that occurs in osteosarcoma." (PMID 35659268, 2022). "In this study, our investigation into whether CCL4 affects osteosarcoma cell migration found that CCL4 promotes integrin αvβ3 expression by downregulating miR-3927-3p through the CCR5 and FAK/AKT/HIF-1α signaling pathway." (PMID 34884541, 2021). "Chemotherapeutic agents in combination with a HIF-1α inhibitor significantly abrogated TGF-β-mediated chemoresistance and enhanced the curative effects, which revealed a potentially promising method for combating osteosarcoma." (PMID 34763667, 2021). "We hypothesized that osteosarcoma cells can produce TGF-β in an autocrine manner, thereby resulting in the activation of the HIF1α pathway." (PMID 34763667, 2021).